GATA2 (GATA binding protein 2)
Diseases named in the same sentence as GATA2 in open-access papers (continued):
Sharing a sentence is not in itself a finding about the gene and the disease.
cancer (continued). "Patients with GATA2hi USC also had significantly better cancer-related and overall survival compared with patients with GATA2lo USC, and GATA2 status was independently predictive of overall survival." (PMID 40168074, 2025). "Some studies have accounted for predicted and validated gene targets like GATA2, SKI, NTRK3, PAK2, AR, SP1, and CDK4 that describe their involvement in cancer progression." (PMID 38741808, 2024). "GATA2 haploinsufficiency includes early-onset multifocal, recurrent, HPV-related genital squamous intraepithelial neoplasia and carcinoma, disproportionately affecting females and frequently involving both the vulva and cervix." (PMID 39267745, 2024). "Intriguingly, among these co-regulated functional categories, GATA2 and SMAD4 jointly modulated the expression of genes involved in multiple cancer-promoting pathways particularly like TGFβ signaling that is required for tumor invasiveness and metastasis." (PMID 37550764, 2023). "These docking results suggests a significant association of binding affinities between the interaction of Imiquimod and TGF-βbeta; signaling targets (Smad2, GATA2, and MAFG) which are mainly involved in the metastaticproperty in cancer cells." (PMID 37822834, 2023). "The correlations between CGA and these TFs in the KM plotter and the Cancer Cell Line Encyclopedia (CCLE) databases were analyzed; GATA2 showed the strongest positive correlation with CGA expression." (PMID 35289315, 2022). "Other genes, including GATA2, GADD45B, and MIR126, are differentially methylated in WD liver and blood, also play a role in epigenetic mechanisms in cancer." (PMID 30709419, 2019). "When the interactions between GATA2 and EVI1 are disrupted, cancer cells have higher apoptosis rates, and CUX1 alters the expression of a cluster of genes and the cell cycle to promote cell proliferation." (PMID 29149895, 2017). "Examination of the cross‐species genomic regions conserved in human tumors, mouse models of cancer, and the MEF immortalization system revealed consistent amplification of five regions containing the COSMIC database‐enumerated oncogenes GATA2 (human chr." (PMID 28202506, 2017). "Among the genes from this last category, two have been identified as “cancer genes” in the COSMIC database (GATA1 and GATA2)." (PMID 27506777, 2016). "Many of the genes, identified in this study as the potential targets of differentially regulated miRNAs are known to be involved in cancer through their effects on cell differentiation (CDK6, LIFR), apoptosis (PIM1) or hematopoiesis (GATA2, TAL1)." (PMID 20459673, 2010). "The GATA2 gene was not included among the genes documented in any KEGG-registered cancer-related pathway." (PMID 41154393, 2025). "Additionally, we found GATA2 transcription factor binding sites in the GAPE-Prom, which regulates pGAPE activity selectively in cancer cells." (PMID 35326649, 2022). "Additionally, we define a new transcription factor, GATA2, to which binding to the GAPE-Prom is indispensable for cancer-selective expression and activity." (PMID 35326649, 2022). "Validating co‐immunoprecipitation (co‐IP) assay indicated endogenous interaction of SPI1 with SPIB, but not with GATA2, in cultured cancer cells." (PMID 34841706, 2021). "GATA3 and GATA2 displayed the highest degree of connectivity with 38 and 19 connections, respectively, and KEGG gene enrichment analysis revealed enrichment for immunity functions and processes, and miRNA in cancer terms." (PMID 35201514, 2021). "Cancer-related genes HDC, GATA2, and SLC45A3 were downregulated and S100A9 was upregulated by CUMS." (PMID 34650925, 2021).
cancer (continued). "We then assessed ALDH1 and GATA-2 protein levels using immunofluorescence to assess whether miR-21 was involved in cancer stemness since both ALDH1 and GATA-2 were found to impact cell survival and tumorigenesis in BCa." (PMID 33557112, 2021). "According to literature searching, GATA2 and TORYAIP1 might represent potential biomarkers and candidate drug targets for the stroma targeted cancer therapy applications." (PMID 33907495, 2021). "Interestingly, all GATA family members besides GATA3 were mostly downregulated in most kinds of cancers, with upregulated vs downregulated study numbers (GATA1 1:7; GATA2 6:39; GATA3 31:36; GATA4 5:18; GATA5 1:17; GATA6 16:37)." (PMID 30872657, 2019). "Although ROBO1-TSS1 also had a GATA2 site, it was a weak non-EC site (QS = 301) from a cancer cell-line." (PMID 30802244, 2019). "ETS1 showed negative immunoreactivity in all types of cancers while GATA2 showed moderate to strong positive immunoreactivity in all tumor types." (PMID 30809433, 2019). "Interestingly, GATA2 mRNA expression is not significantly correlated with either PEAK1 or VEGFR2 mRNA in most cancer types, which is consistent with our findings that PEAK1 regulates GATA2 protein degradation at the post-translational level." (PMID 29872538, 2018). "The GATA family (GATA Binding Protein), which includes GATA2, GATA3, and GATA6, governs critical cellular processes such as cell migration, epithelial-to-mesenchymal transition (EMT), and metastasis, all of which play important roles in cancer formation and progression." (PMID 41155227, 2025). "Notably, well-known cancer-related TFs emerged, such as MYCN, GATA2, and ESR1." (PMID 37370684, 2023). "Importantly, since GATA2 functions upstream of NR3C1 and other enzalutamide-induced cancer-promoting genes (e.g. SLC7A11 and LAMP3), targeting GATA2 maybe a better strategy for improving AR-targeted therapy by enzalutamide." (PMID 31501863, 2019). "Among the 5 core TFs identified in the largest TNBCac co-regulation module, ETS1 and GATA2 seemed to be not generally crucial in survival and growth of cancer cells, which may be due to nonlinear dose-dependence or insufficient shRNA interference efficiency." (PMID 28423538, 2017). "We show that routine GATA2 IHC identifies 33% of FIGO stage I USCs with high GATA2 expression (GATA2hi) and that patients with GATA2hi USCs do not experience cancer recurrence after hysterectomy, even when adjuvant therapy is omitted." (PMID 40168074, 2025). "The SCENIC results suggest that normal and cancer epithelia share canonical luminal transcription factors (TFs) such as HOXB13, GATA2, AR." (PMID 38483933, 2024).
tumor (86 papers, 2007 to 2025). "For example, tumour cells exhibited high activity of regulons regulated by TFs such as GATA2, NFIL3 and E2F1, which are associated with cell proliferation and survival." (PMID 40099956, 2025). "Research also indicates that GATA2 can act as a tumor suppressor, and its inactivation due to mutations can accelerate disease progression." (PMID 40981111, 2025). "The results revealed that patient group with GATA2 copy number gain was greatly associated with higher Gleason score, advanced tumor stage, elevated PSA levels and lymph nodes." (PMID 37550764, 2023). "These neoplasms tend to show fewer somatic mutations and a different molecular landscape compared to non-GATA2 MDS/AML." (PMID 36900380, 2023). "Robust association of GATA2 amplification and upregulation with metastasis in PCa indicates its function in PCa tumorigenesis and tumor progression." (PMID 37550764, 2023). "Compared with patients with low GATA2 expression, patients with high GATA2 expression had significantly decreased risk of tumor recurrence (H.R. = 0.63, 95% CI = 0.43∼0.90, p = 0.012) and patient death (H.R. = 0.67, 95% CI = 0.47∼0.95, p = 0.026)." (PMID 24498120, 2014). "A great proportion of patients (126/240, 52.5%) with high risk of tumor recurrence received prophylactic therapy after resection, which would reasonably obscure the prognostic influence of intratumoral GATA2." (PMID 24498120, 2014). "Although primarily considered as important transcriptional regulators during embryogenesis, GATA-2, -3 and -4 have also been associated with tumours." (PMID 19707195, 2009). "Comparisons of stage 4S tumours vs stage 4 disclosed a significant association only for GATA-2 with higher transcript levels in the more favourable 4S tumours (P=0.019)." (PMID 19707195, 2009). "Some genes encode proteins with functions related to signal transduction (PIK3R3, MAPK8IP1, and GATA2), and one gene encodes a protein that regulates tumor invasion and metastasis (TIMP2)." (PMID 17498291, 2007). "Furthermore, inhibiting GATA2-associated signaling pathways in mice with KRAS mutant NSCLC leads to tumor regression." (PMID 41514651, 2025). "La deficiencia de GATA2 se ha relacionado con neoplasias malignas hematológicas." (PMID 39836831, 2024). "Abnormal GATA2 expression and somatic mutations are linked to tumor promotion and inhibition." (PMID 38644410, 2024). "Of note, in the 14 primary cases with only tumor material available, there were 2 cases with GATA2 mutations at a variant allele frequency (VAF) of > 40%, suggesting that they may be germline events." (PMID 29146900, 2017). "After a leukemic transcriptional program is established, however, Gata2 acts as a tumor suppressor, performing its normal role to limit proliferative excess in hematopoietic progenitors; this is probably the reason that inactivation of the second allele promotes tumor progression." (PMID 38648485, 2024). "Furthermore, high expression levels of GATA2 in PCa displayed highly robust associations with tumor progression to metastasis, higher Gleason score, advanced tumor stage and elevated PSA level." (PMID 37550764, 2023). "Overall, in 77% of cases, metastatic USC tumors have equal to or less GATA2 expression than the primary tumor, but there is substantial variability in GATA2 expression in USC metastases." (PMID 40168074, 2025). "The percentage of GATA2+ USC tumor nuclei ranged from 0% to 100%, with an initial inflection point at 15% that we later found clearly separated patients by survival." (PMID 40168074, 2025). "It will be critical to ensure that GATA2 IHC can be easily performed and scored on full sections of tumor such as those evaluated in routine surgical pathology practice, and that IHC labeling is uniform across additional institutions and centers." (PMID 40168074, 2025).
tumor (continued). "According to the UALCAN database, the expression levels of PVT1, hsa-miR-143–3p, CDK1, FOXC1, YY1, and GATA2 show statistically significant differences between primary tumor samples and normal samples in the TCGA-LUAD dataset." (PMID 41080754, 2025). "To validate our findings, we employed Kaplan-Meier survival curves and ROC curves to analyze the key genes associated with C2 tumor cell subtypes, including the top five transcription factors (IGF2, PRRX1, MAFB, LBX2, GATA2, MAFG)." (PMID 39896800, 2024). "GATA2 expression inversely correlated with DNA methylation at the multiple CG sites in the 5′-UTR region (P-value: < 0.001) in adjacent non-tumor tissues from AA men (middle and right panels: left bottom quadrant)." (PMID 38566104, 2024). "The downregulation of ALDOB by STAT3 and GATA2 promotes enhanced glycolytic flux, which is essential for meeting the increased energy demands of rapidly dividing tumor cells." (PMID 39348357, 2024). "To further verify the role of GATA2 in tumor cell proliferation in vivo, we subcutaneously inoculated the shRNA-mediated GATA2 knockdown 22Rv1 cells or cells with shRNA-scramble into SCID male mice by right flank injection." (PMID 37550764, 2023). "The infiltration of CD8+ T cells, T cells, tumor-associated macrophages (TAMs), M1 macrophages, dendritic cells, NKs, Th1, Th2, Th17, and Tregs in KIRC was strongly correlated with GATA2 expression." (PMID 36961416, 2023). "Collectively, the knockdown of GATA2 and Ventx attenuated cell proliferation and tumor growth, improved patient survival, and boosted the immunosuppression by drugs in tumor samples." (PMID 35269883, 2022). "At the CRPC stage where AR signaling is often still central to tumor growth, GATA2 continues to act as a crucial cofactor for AR transcriptional activity and colocalizes with both full-length AR and AR splice variants on the chromatin." (PMID 36212399, 2022). "ADGRG6 also promoted tumour-stromal angiogenesis and hypoxia-induced retinal angiogenesis through the GATA2/STAT5/ VEGF/MAPKs signalling pathway." (PMID 34809653, 2021). "Further analysis identified a somatically acquired 101 kb focal deletion located 285 kb downstream of the TSS of GATA2 in the tumor cells." (PMID 35087776, 2021). "The authors found regulatory regions under GATA2 control in both PD-L1 and PD-L2 genes, suggesting common mechanisms regulated tumor cell-intrinsic expression of the two PD1 ligands." (PMID 34572014, 2021). "Recently, nanoparticles carrying siRNA targeting GATA2 significantly reduced tumour growth in a xenograft murine model of NSCLC harbouring oncogenic KRAS mutations.These promising results require further exploration." (PMID 27191720, 2016). "GATA2 expression was also reduced in tumor tissues in the majority of stage T2 samples, although in stage T3 tumors, expression was not consistent." (PMID 20426842, 2010). "Therefore, we established 15% GATA2+ nuclei as a cutoff and assigned all USCs with fewer than or equal to 15% GATA2+ nuclei as GATA2lo, and USCs with greater than 15% GATA2+ tumor nuclei as GATA2hi." (PMID 40168074, 2025). "IDH mutations predominantly impact metabolic pathways but may also engage with transcription factors such as GATA2, thereby affecting tumor behavior and therapeutic responses." (PMID 41154393, 2025). "Additionally, GATA2 governs endothelial cell fate and angiogenesis, fostering tumor growth and metastasis." (PMID 41514651, 2025). "In addition, we discovered that cluster 2 is highly associated with some tumor stemness-related transcription factors: WNT5A, WNT10A, GATA2, and FOSL2." (PMID 38339238, 2024).
tumor (continued). "GATA2 expression was negatively correlated with DNA methylation at specific loci in adjacent non-tumor tissues of AA men, suggesting that DNA methylation can regulate GATA2 expression (left panel: left bottom quadrant, dots represent correlation coefficient estimate for individual clinical samples)." (PMID 38566104, 2024). "Furthermore, we examined the expression profile of GATA2 in two GEO datasets, uncovering a substantial down-regulation of GATA2 in tumor tissues compared to their normal counterparts." (PMID 38879709, 2024). "GATA2 may also play critical roles in maintaining adrenergic features in poorly differentiated tumours." (PMID 36980710, 2023). "GATA2/5/6 expression changed noticeably throughout the tumor stages, according to correlation analysis of TCGA data using the Gene Expression Profiling Interactive Analysis (GEPIA) database, whereas GATA1/3/4 expression showed no discernible variations among tumor stages." (PMID 36961416, 2023). "Herein we proved a robust evidence in support of in vivo interaction between GATA2 and SMAD4 and thus sought to unravel the mechanistic roles of TGFβ1/SMAD4 in the GATA2-dependent context in PCa tumor progression to advanced stages and to understand how GATA2 and SMAD4 mediate inherited PCa risk." (PMID 37550764, 2023). "This may be due to the presence of genetically diverse clones within a tumor, with each population responding differently to chemotherapy, resulting in the emergence of high-GATA2-expressing clones." (PMID 35289315, 2022). "Dilazep, a vasodilator that is used to treat patients with hypertension, cardiovascular, and renovascular disorders, is a second pharmaceutical agent that blocks GATA2 DNA-binding, suppresses the expression of AR, and reduces tumor growth in a murine xenograft model of CRPC." (PMID 36212399, 2022). "Abnormal GATA2 transcription makes B-ALL tumor cells more myeloid-like and could contribute to leukemogenesis by activating downstream target genes." (PMID 35087776, 2021). "Thus, we observed the tumor suppressive effects of GATA2 in two germline Gata2 genetic mouse models." (PMID 34633564, 2021). "These hub biomolecules of tumor stroma network, AR, GATA2, miR-124, TOR1AIP1, ESR1, EGFR, STAT1, miR-192, GATA3, COL1A1, may give crucial information about tumorigenesis." (PMID 33907495, 2021). "One hypothesis is that GATA2 overexpression drives PD-L2 expression that could inhibit anti-tumor immunity." (PMID 32493985, 2020). "This conclusion was supported by various lines of evidence: (i) loss of GATA2 reduced the viability of Ras-mutated NSCLCs, but not of WT NSCLCs; (ii) in KRAS-driven NSCLC mouse model, GATA2 loss strongly reduced tumor development." (PMID 30060526, 2018). "The role of GATA2 as a tumor suppressor remains to be defined." (PMID 29029492, 2017). "Interestingly, in tumor S2, two driver genes, GATA2 and STK11, were located in the ancestor subclone, and STK11 also harbors neo‐epitope." (PMID 27998038, 2017). "Additionally, we carried out a stratified analysis by the TNM stage (I/II and III/IV), to determine the prognostic significance of GATA2 rs2335052 genotypes in different tumor stages." (PMID 26287967, 2015). "Besides, our results also revealed a significant correlation of intratumoral GATA2 expression with other pivotal parameters related to local invasion (e.g. tumor capsule) and distant metastasis (e.g. tumor thrombi)." (PMID 24498120, 2014). "Further analysis indicated that intratumoral GATA2 remained to be an independent predictor of tumor recurrence and patient death in subgroups of patients receiving prophylactic therapy (p = 0.039 for TTR and p = 0.005 for OS) or not (p = 0.003 for TTR and p = 0.027 for OS)." (PMID 24498120, 2014). "Additionally, targeting GATA2-mediated angiogenesis could disrupt tumor vascularization and sensitize tumors to anti-angiogenic therapies." (PMID 41514651, 2025). "Targeting GATA2 may help reduce the inhibitory effects of PD-L2 in the tumor microenvironment." (PMID 36961416, 2023).